SLCO2B1 (solute carrier organic anion transporter family member 2B1)
Diseases named in the same sentence as SLCO2B1 in open-access papers:
SLCO2B1 is named in the same sentence as 51 diseases in open-access papers, as found by Europe PMC text mining. Sharing a sentence is not in itself a finding about the gene and the disease. The quoted sentences say what the papers report.
prostate carcinoma (11 papers, 2011 to 2023). A carcinoma that arises from epithelial cells of the prostate gland. "Prostate cancer cell lines carrying the risk allele for rs1077858 also exhibited an increased expression of SLCO2B1." (PMID 37435458, 2022). "Among them, high expression of SLCO2B1 is known to associate with the resistance to androgen deprivation therapy in prostate cancer (PCa)." (PMID 29581838, 2018). "However, genetic studies revealed that patients somatically carrying the variant allele of SLCO2B1 (SNP rs12422149, c.935G>A) have a higher risk of dying from prostate cancer." (PMID 32806706, 2020). "It remains to be determined whether genetic variants of SLCO2B1 can be used as biomarkers for the response to abiraterone treatment in advanced prostate cancer." (PMID 32806706, 2020). "In prostate cancer, the mRNA of SLCO2B1 is one of six SLC transporters shown to be upregulated compared to nonmalignant transformed tissue." (PMID 32806706, 2020). "Furthermore, SLCO2B1 mRNA expression was significantly higher in advanced prostate cancer with high a Gleason score." (PMID 36839686, 2023). "We thus made the hypothesis that gene polymorphisms occurring in CYP17A1, SLCO2B1, and SLCO1B3 could influence AA antitumor activity in advanced prostate cancer." (PMID 36839973, 2023). "This is the first study indicating that SLCO1B1, SLCO1B1, and SLCO2B1 is significantly expressed (or expression is reduced) in a variety to tumors, including: colon cancer, liver cancer, pancreatic cancer, prostate cancer, testicular cancer, and thyroid cancer." (PMID 21625523, 2011). "The presence of SNPs in genes involved in the membrane transport of testosterone and dehydroepiandrosterone (DHEA), namely SLCO2B1 and SLCO1B3, has been reported as having an influence on the efficacy of androgen deprivation therapy (ADT) in prostate cancer." (PMID 36839973, 2023). "Lastly, there are already currently available clinical and genetic tools and technologies to evaluate prostate cancer outcomes based on HSD3B1, SLCO2B1, and SRD5A2 genotype and their relationships to disease, which will guide future biomarker-driven treatment." (PMID 37435458, 2022). "Moreover, mRNA expression levels of SLCO1B1, SLCO1B3, SLCO2B1 and SLCO4C1 were found to be higher in castration-resistant prostate cancer metastases as compared to in untreated prostate cancer." (PMID 36839686, 2023). "However, other notable trends were SLCO2B1 decreased expression by stage in pancreatic cancer, SLCO1B3 increased frequency by stage in prostate cancer, and SLCO1B1 decreased expression by stage in liver cancer." (PMID 21625523, 2011).
breast carcinoma (7 papers, 2011 to 2021). "The expression of SLCO2B1 was shown to be significantly correlated with histological grade in ER+ breast cancer." (PMID 33892787, 2021). "Despite previously published reports, SLCO1B3, SLCO2B1, and SLCO1B1 were not highly expressed in our breast cancer samples." (PMID 21625523, 2011).
asthma (4 papers, 2011 to 2021). "A nonsynonomous polymorphism, rs1242149 (c935G > A), in SLCO2B1 has been found to associate with significantly reduced plasma concentrations of montelukast and Asthma Symptom Utility Index (ASUI) in patients with asthma treated with montelukast for 6 months." (PMID 21490765, 2011). "KEGG pathway analysis results and GSVA results show that genes related to allograft rejection, asthma, and autoimmune thyroid disease pathways were enriched or upregulated in the LAPTM5, C1QC, SLCO2B1 and CSF1R high expression groups." (PMID 33428598, 2021).
liver cancer (4 papers, 2011 to 2025). An epithelial or non-epithelial malignant neoplasm that arises from the liver. "In the liver and pancreas, lower mRNA expression of SLCO2B1 in liver cancer was associated with decreasing differentiation and significantly lower expression of SLCO2B1 was seen in pancreatic cancer compared with normal pancreatic tissue." (PMID 32388639, 2020). "SLCO2B1 expression decreased significantly in pancreatic cancer [27.5 (9.5 to 45) versus 9.1 (5.5 to 12.8); 3.0 fold decrease; P = 0.05] and liver cancer [47.3 (16.1 to 78) versus 17.0 (4.9 to 29); 2.7 fold decrease; P = 0.04]." (PMID 21625523, 2011). "Based on expression frequency, SLCO2B1 was lower in liver cancer (P = 0.04) which also trended lower with decreasing differentiation (P = 0.004) and lower magnitude in pancreatic cancer (P = 0.05)." (PMID 21625523, 2011). "SLCO2B1 expression was also correlated negatively to differentiation in liver cancer (47 (4.4 to 82), 13 (−3.2 to 28), 3.1 (1.4 to 4.7), and 1.7 (N/A) for normal tissue and well, moderately, and poor differentiated tumor tissue respectively; P = 0.005) up to a 26-fold change." (PMID 21625523, 2011).
Myalgia (2 papers, 2017 to 2018). "Concordant with these observations, gene variants of SLCO1B1 and SLCO2B1 were observed with increased frequency in patients with statin-associated myalgia." (PMID 28771594, 2017). "This mechanistic scenario is further bolstered by the discovery that a number of single nucleotide polymorphisms (e.g., SLCO1B1, SLCO2B1 and RYR2) associated with statin myalgia and myositis were observed with increased frequency among patients with statin myalgia." (PMID 28771594, 2017).
ovarian carcinoma (2 papers, 2018 to 2022). A malignant neoplasm originating from the surface ovarian epithelium. "Furthermore, the present findings suggested two networks of SLCO and ABC-transporter coding genes (SLCO2B1/ABCC3 and ABCB2/ABCB3/ABCC3/HER-2) and demonstrated the expression of SLCO1B7 in ovarian cancer samples." (PMID 30131693, 2018). "Notably, ubiquitously expressed SLCO2A1, SLCO2B1, SLCO3A1, and SLCO4A1 genes have been identified in ovarian cancer." (PMID 30131693, 2018).
pancreatic cancer (2 papers, 2011 to 2020). "For example, DHEA-S inhibits pancreatic cancer growth, which might explain the observation that SLCO2B1 expression is reduced in pancreatic cancer." (PMID 21625523, 2011).
acute kidney injury (1 paper, 2023). Sudden and sustained deterioration of the kidney function characterized by decreased glomerular filtration rate, increased serum creatinine or oliguria. "For instance, functional SNPs of SLCO1B1 have been shown to decrease hepatic uptake activity, while the expression level of SLCO2B1 substantially declined in the small intestine of rats with acute kidney injury." (PMID 37759782, 2023).
ileum cancer (1 paper, 2017). "Other protein-encoding genes (FGL2, CTSB, TPP1, SLCO2B1, NARF and JTB) have disease related functions, such as viral hepatitis and ileum cancer." (PMID 28401895, 2017).
inflammatory bowel disease (1 paper, 2022). A spectrum of small and large bowel inflammatory diseases of unknown etiology. "For example, in colon of patients with inflammatory bowel disease, the mRNA expression levels of SLCO4A1, and also other SLCOs, e.g., SLCO2B1 were upregulated, while the expression of transporters from other families was downregulated." (PMID 36105223, 2022).
liver diseases (1 paper, 2025). "SLCO1B1, SLCO1B3, and SLCO2B1 are highly expressed in the liver and play key roles in many liver diseases." (PMID 40734706, 2025). "SLCO1B1, SLCO1B3, and SLCO2B1 are highly expressed in the liver and play key roles in various liver diseases." (PMID 40734706, 2025).
malaria (1 paper, 2017). Malaria is a serious and sometimes fatal disease caused by a parasite that commonly infects a certain type of mosquito which feeds on humans. "The nonsynonymous 935G>A SNP in SLCO2B1 was associated with parasitemia clearance rate in malaria treatment in this study population." (PMID 28975866, 2017).
metastatic disease (1 paper, 2018). "It will be ideal to compare SLCO2B1 expression level between primary tumor with and without metastasis because EMT is a well-known mechanism in metastatic disease and cancer progression, and validate SLCO2B1 expression level and recurrence using another cohort." (PMID 29581838, 2018).
parasitemia (1 paper, 2017). "ABCB1 and SLCO2B1 genes were associated with the clearance rate over treatment time in the model adjusting for age, gender, co-medication, parasitemia baseline level and genetic ancestry." (PMID 28975866, 2017). "Significant interaction between SLCO2B1 genotypes and treatment over time for parasitemia clearance rate on day 2 were observed (pFDR = 0.002)." (PMID 28975866, 2017). "Mean parasitemia over treatment time according to ABCB1 and SLCO2B1 genes." (PMID 28975866, 2017).
thrombotic thrombocytopenic purpura (1 paper, 2023). "SLCO2B1 and SLCO1B3 are involved in the steroidal hormone uptake, and thrombotic thrombocytopenic purpura (TTP) is linked with three SNPs present in SLCO2B1 expressed in various tissues." (PMID 37858151, 2023).
thyroid cancer (1 paper, 2011). "SLCO2B1 expression was also significantly related to liver and thyroid cancer." (PMID 21625523, 2011). "SLCO2B1 expression increased with stage up to a 29 fold-difference in thyroid cancer (P = 0.04)." (PMID 21625523, 2011). "SLCO2B1 also had a higher frequency in thyroid cancer (67%) than normal (0%) and expression increased with stage (P = 0.04)." (PMID 21625523, 2011).
cancer (17 papers, 2011 to 2025). A tumor composed of atypical neoplastic, often pleomorphic cells that invade other tissues. "Using UALCAN, we analyzed the SLCO2B1 transcript expression level in the normal liver tissues from healthy individuals and cancer liver tissues in HCC patients from different subgroups classified by gender, N stage, disease stage, and disease grade." (PMID 40734706, 2025). "Using UALCAN, we further examined protein expression levels of SLCO1B1, SLCO1B3, and SLCO2B1 in normal liver tissues from healthy individuals and cancer liver tissues from HCC patients, based on data from the CPTAC dataset." (PMID 40734706, 2025). "Analysis of the TCGA Liver Hepatocellular Carcinoma dataset (TCGA’s Pan-Cancer Atlas) revealed a low mutation and amplification frequency in HCC for SLCO1B1 (0.57% vs. 0.29%), SLCO1B3 (0.86% vs. 0.29%), and SLCO2B1 (0.57% vs. 0.86%), respectively." (PMID 40734706, 2025). "Analysis of the TCGA Liver Hepatocellular Carcinoma dataset (TCGA’s Pan-Cancer Atlas) revealed a low mutation and amplification frequency in HCC for SLCO1B1 (0.57% vs. 0.29%), SLCO1B3 (0.86% vs. 0.29%) and SLCO2B1 (0.57% vs. 0.86%)." (PMID 40734706, 2025). "In bone, SLCO2B1 has been detected in both benign and malignant tumours, with significantly higher mRNA levels in aneurysmal bone cysts (benign) as compared with osteosarcomas (malignant)." (PMID 32388639, 2020). "Statins, a class of cholesterol-lowering medications that inhibit 3-hydroxy-3-methl-glutaryl-coenzyme A reductase, are also substrates of SLCO2B1 and have been shown to act as an anticancer drug in various types of cancers." (PMID 29581838, 2018). "Since high expression of SLCO2B1 associated with cancer recurrence only in GS ≥ 8 patients, clinicopathological features were compared between SLCO2B1 high and low expression groups in PCa patients with GS ≥ 8 to investigate whether certain populations associated with SLCO2B1 expression." (PMID 29581838, 2018). "We completed a study examining SLCO1B3, SLCO1B1 and SLCO2B1 mRNA expression in 381 primary, independent patient samples representing 21 cancers and normal tissues." (PMID 21625523, 2011). "Using UALCAN, gene transcript expression levels of SLCO1B1, SLCO1B3, and SLCO2B1 were shown to be significantly downregulated in the clinic-pathological characteristics (gender, nodal metastasis status, cancer stages and tumor grade) in HCC patients compared to normal counterparts." (PMID 40734706, 2025). "OATP2B1 as a modifier of abiraterone activity in cancer cells was further investigated in a clinical trial, where the genetic variants of SLCO2B1 namely the coding rs12422149 (c.935G>A) and the intronic rs1789693 correlated with tissue concentrations of abiraterone." (PMID 32806706, 2020). "Furthermore, we elucidated that high SLCO2B1 expression tumors enriched EMT related gene sets as well as key cancer signaling pathways related gene sets that promote EMT." (PMID 29581838, 2018). "The data indicated that all analyzed SLCO genes exhibited significantly increased expression levels (and/or were more often detectable) in cancer compared with benign tissue samples (FDR ranging from 0.038 for SLCO2B1 to 5.3 × 10−12 for SLCO3A1 and SLCO4A1, respectively)." (PMID 30131693, 2018). "Notably, for other tumor entities such as colorectal neoplasia, liver, or breast cancer, SLCO2B1 genetic variants have not been associated with a risk of developing cancer." (PMID 32806706, 2020). "Therefore, it would be tempting to investigate the effects of CAR antagonists on transporter expression in cancer cells with a low abundancy of SLC22A1 and SLCO2B1." (PMID 36839686, 2023). "In addition, the mRNA data in the Cancer Cell Line Encyclopedia database showed that the expression of C1QC, CSF1R, LAPTM5 and SLCO2B1 mRNA was significantly lower in LUSC cell lines (n=23) compared to lymphoid cell lines (n=167)." (PMID 33428598, 2021).
cancer (continued). "Nevertheless, SLCO2B1 expression has been shown in several cancers with some differences between malignant and non-malignant tissues." (PMID 32388639, 2020). "SLCO2B1 was not expressed significantly different in cancer compared to normal tissue." (PMID 21625523, 2011).
tumor (15 papers, 2011 to 2025). "The mRNA expression of C1QC, CSF1R, LAPTM5 and SLCO2B1 was negatively associated with tumor purity." (PMID 33428598, 2021). "Since SLCO2B1 expression was significantly higher in GS high tumors, we hypothesized that SLCO2B1 expression was associated with tumor aggressiveness in GS high tumors." (PMID 29581838, 2018). "We selected four hub genes, LAPTM5, C1QC, CSF1R, and SLCO2B1, and analyzed their correlation with the tumor infiltration of 22 immune cell subsets using CIBERSORT and the prognosis of different immunity-related LUSC patient subtypes." (PMID 33428598, 2021). "The expression of LAPTM5, CSF1R, SLCO2B1 and C1QC was negatively associated with the tumor purity in the LUSC samples." (PMID 33428598, 2021). "Expression frequencies were determined for SLCO1B3, SLCO1B1, and SLCO2B1, and the percent of normal or tumor tissues expressing SLCOs are reported." (PMID 21625523, 2011). "SLCO2B1 expression in normal breast tissue and tumours is also supported by microarray analysis." (PMID 32388639, 2020). "The expression level of SLCO2B1 was significantly higher in advanced characteristics including Gleason Score (GS ≤ 6 vs GS = 7; p = 0.047, GS = 7 vs GS ≥ 8; p = 0.002), pathological primary tumor (pT2 vs pT3/4; p < 0.001), and surgical margin status (positive vs negative; p = 0.013), respectively." (PMID 29581838, 2018). "Greater expression of SLCO2B1 leads to increased DHEAS transport into cells in PCa cell lines, and overexpression of SLCO2B1 increases tumor DHEAS accumulation in a PCa murine model." (PMID 29581838, 2018). "As some tumor tissues had similar SLCO expression frequencies as normal tissues, we also ascertained if the magnitude of SLCO expression was different for SLCO1B1, SLCO1B3, and SLCO2B1." (PMID 21625523, 2011). "Conversely, another study analysing 120 tumour and 23 normal breast tissue samples using qPCR found higher expression in malignant versus non-malignant tissues, and that expression of SLCO2B1 increased with tumour grade, though neither of these findings reached statistical significance." (PMID 32388639, 2020). "However, we were unable to find a dataset which has SLCO2B1 expression level of primary tumor with and without metastasis, as well as SLCO2B1 expression level with patient recurrence-free survival." (PMID 29581838, 2018). "A recent study highlighted the overexpression of OATP2B1 (known as a prostaglandin PGE2 transporter, coded by the SLCO2B1 gene), which is substantially expressed in the intestine, in CRC biopsies (19 patients enrolled, in the neoplasia group and 8 in the control group) (p = 0.017)." (PMID 29282011, 2017). "Based on these findings, we proposed that LAPTM5, CSF1R, SLCO2B1 and C1QC are mainly expressed in immune cells rather than LUSC cells in tumor samples." (PMID 33428598, 2021).
SLCO2B1 also shares sentences with these, for which no sentence is quoted: colon carcinoma (3 papers); hepatic carcinoma (3); myopathy (3); COVID-19 (2); gastric cancer (2); prostate tumor (2); autoimmune disease (1); autoimmune thyroid disease (1); bacterial infection (1); bone cysts (1); brain disease (1); brain tumours (1); cholestasis (1); chorioamnionitis (1); colorectal cancer (1); depressive disorder (1); diabetes (1); glioma (1); hepatitis C infection (1); infection (1); invasive ductal carcinomas of the breast (1); melanoma (1); myositis (1); nonalcoholic steatohepatitis (1); Obesity (1); Plasmodium vivax malaria (1); preeclampsia (1); rhabdomyolysis (1); sarcoma (1); testicular cancer (1).
A further 3 diseases each share a sentence with SLCO2B1 in 1 paper.